EGFR (epidermal growth factor receptor)
Diseases named in the same sentence as EGFR in open-access papers (continued):
Sharing a sentence is not in itself a finding about the gene and the disease.
tumor (continued). "The aim of this study was to detect HER2 amplification in circulating tumor DNA (ctDNA) from patients with CRC and acquired resistance to anti-EGFR antibody therapy." (PMID 26657506, 2016). "Also, some data have shown that human epidermal growth factor receptor, a family of tyrosine kinase receptors, expressed in normal tissues and in many types of cancer in humans and canines and its downstream pathway regulates migration and tumor invasion by ECM components." (PMID 27490467, 2016). "During EGFR-TKI treatment, we observed that the plasma c-Met level decreased at the time of the best tumor response and increased with PD, particularly in EGFR-TKI-resistant patients with c-Met positivity." (PMID 27213587, 2016). "A combination of ficlatuzumab plus cetuximab therapy resulted in complete tumor response in all animals, indicating a role for dual inhibition of the HGF and EGFR pathways." (PMID 27669306, 2016). "Our results confirm these previous observations on the role of IL-8 in resistance to EGFR inhibition and further expand them by demonstrating that upregulation of p38 MAPK signaling is responsible for enhanced IL-8 secretion in resistant tumor cells." (PMID 27248176, 2016). "Based on the involvement of IL10 in the formation of tumor microenvironment and tumor development, we studied how IL10 increases EGFR expression." (PMID 26956044, 2016). "With overexpressing EGFR and HER-2, tumor cells show aggressive cell growth due to the increased potential for EGFR/HER-2 hetero-dimerization and signaling." (PMID 27897231, 2016). "In the mice intracranially pre-inoculated with EGFR-expressing MDA-MB-231 cells, intratumoral administration of either EGFR-CAR-transduced NK-92 cells or oHSV-1 mitigated tumor growth." (PMID 27050072, 2016). "Cetuximab, a clinically approved, epidermal growth factor receptor-specific monoclonal antibody, activates NK cells through interactions with FcγRIII and facilitates ADCC of tumor cells." (PMID 26928328, 2016). "C-MMAE and T-MMAE bound and restricted MMAE activity and toxicity to EGFR and HER2 expressing tumour cells, respectively." (PMID 27698471, 2016). "Statistically significant differences emerged in the distribution of EGFR, CCND1 and ESR1 CNVs according to ER, HER2, MIB1 and tumor size (T) status." (PMID 27765917, 2016). "Overall, these results demonstrate the substantial efficacy of combined MET and EGFR inhibition in abrogating downstream RTK signaling, reducing tumor progression, and reducing tumor response variability." (PMID 27655711, 2016). "There was an overexpression of epidermal growth factor receptor (EGFR) in > 50% of patients with TNBC, and it was found from a tumor microarray study that patients with significantly elevated expression of EGFR were more prone to lung metastasis." (PMID 27322074, 2016). "Patient 219, similarly, showed marked tumour growth and occurrence of brain metastasis while on EGFR TKI, but later responded to whole-brain radiotherapy as measured by the reduction in tumour size." (PMID 27325363, 2016). "Preclinical positron emission tomography (PET) imaging revealed a mismatch between in vivo epidermal growth factor receptor (EGFR) expression and EGFR antibody tracer tumor uptake." (PMID 27602494, 2016). "In both normal and tumor cells, MMP-9 has been shown to be secreted in response to EGFR activation via exogenous ligands." (PMID 27888810, 2016). "In the NFH group, age, differentiation, venous tumor emboli, nervous invasion, tumor location, tumor size, Borrmann type, TNM stage, p21 overexpression, Neu/Her-2 overexpression, and EGFR overexpression were significantly correlated with prognosis." (PMID 27127887, 2016). "To correlate this finding with tumor malignancy, we haveconfirmed HIF-1α, HIF-2α, and EGFR expression in sections from the samefrozen sample by western blot analysis." (PMID 27303300, 2016).
tumor (continued). "In this study, we observed higher rates of EGFR and CK5/6 positivity among high Ki67 expressing tumours, providing the most definitive evidence to date in support of these associations." (PMID 27499923, 2016). "A moderate to intense cytoplasmic staining of tumor cells (H score = 2 to 3) with EGFR and MET Abs, and a moderate to intense nuclear staining of tumor cells (H score = 2 to 3) with CDK6 Abs were considered to define IHC positivity." (PMID 27329726, 2016). "V2 isoform expression can inhibit tumor cell proliferation and metastasis through EMT modulation and by down-regulating EGFR signaling through ERK/GSK3β pathways." (PMID 27490467, 2016). "As such, EGFR mutation positivity cannot be discounted as a possible reason for the prolonged stable disease observed in the two NSCLC patients (mutation status unknown), although this response is not typical of the tumour regressions observed in erlotinib treated EGFR activating mutation patients." (PMID 27036206, 2016). "Mechanistically, we found that TAZ promoted cell proliferation and tumor formation of GBM cells by potentiating the EGFR/AKT/ERK pathway, whereas all the effects were blocked by the EGFR inhibitor Erlotinib." (PMID 27167112, 2016). "After the failure of epidermal growth factor receptor-tyrosine kinase inhibitor (EGFR-TKI), rebiopsy of the tumour should be performed to determine the next treatment strategy." (PMID 27543609, 2016). "Several epithelial markers (EGFR, EpCAM, CK18, CK19) were downregulated in CTCs compared to the corresponding tumor tissue." (PMID 27029058, 2016). "We investigated immediate-early effects of EGFR-TKI treatment in mutant EGFR-driven transgenic mouse models by FDG-PET and MRI and correlated the effects on the tumor and the tumor microenvironment." (PMID 27494838, 2016). "Patients who have genomic tumor aberrations, such as EGFR or ALK, and are receiving an approved EGFR- or ALK-directed therapy should have disease progression prior to receiving nivolumab." (PMID 28090370, 2016). "Here genetically engineered mouse models (GEMMs) models, and patient-derived xenografts (PDXs) of KRAS, EGFR, and EML-ALK-driven tumours have been instrumental in understanding the key aspects of NSCLC biology." (PMID 27350784, 2016). "EGFR activation elicits its effects partially via PIK3CA/AKT/mTOR pathways, which promote tumor proliferation, invasion, and migration." (PMID 27554588, 2016). "Recent study from our laboratory showed that PKG II had an inhibitory effect on EGFR activation and consequently inhibited the EGF/EGFR induced MAPK, PLCγ and PI3K/Akt mediated signal pathways in a variety of tumor cells." (PMID 27147579, 2016). "We detected specific expression for EGFR, MET and CDK6 proteins in tumor cells of all tumor samples studied by IHC." (PMID 27329726, 2016). "Multivariate Cox analysis identified five significant variables: EGFR (p = 0.016), CK5/6 (p = 0.018), Ki-67 (p = 0.048), tumor stage (p = 0.010), and nodal stage (p = 0.003)." (PMID 26930401, 2016). "Similar inhibition of A549-derived tumor growth has been observed with cationic liposome-delivered shRNAs targeting FAK and EGFR with reduced microvessel density being observed in treated tumors." (PMID 26962872, 2016). "Three months after EGFR-TKI treatment, tumor response to treatment was evaluated and PR in 61 (79.2%), SD in 8 (10.4%), and PD in 8 (10.4%) patients were observed." (PMID 27368002, 2016). "The epidermal growth factor receptor(EGFR) pathway plays an important role in cell proliferation, differentiation and migration and has been extensively researched in its capacity in tumor progression." (PMID 27014908, 2016). "A bispecific EGFR/MET antibody, called JNJ-61186372, has recently showed a potent inhibition of EGFR downstream effectors, resulting in tumor regression in NSCLC xenografts." (PMID 27528792, 2016).
tumor (continued). "Epidermal growth factor receptor (EGFR) is a known activator of cell proliferation, migration and tumor invasion in several cancers, including the one originating from the breast." (PMID 27500205, 2016). "The simultaneous blockade of EGFR and VEGFR (i.e., AEE788) has been tested with radiation and can lead to significant tumor growth delay in DU145 cells." (PMID 26909338, 2016). "EGFR induces phosphorylation of Y393 in AGO2 to inhibit miRNA maturation, leading to tumor cell survival." (PMID 27701455, 2016). "As EGFR structural and copy number variation is a common feature of GBM, we performed WGS on patient #8 tumour and blood samples, elucidating major (>50×) copy number amplification of EGFR and the surrounding genomic locus." (PMID 27843499, 2016). "To identify the effect of soluble c-Met levels on EGFR-TKI resistance, we divided the 49 patients into two groups according to c-Met status in the resistant tumor tissue." (PMID 27213587, 2016). "Stimulated by growth factors EGF and HGF respectively, EGFR/Ras/Raf/MEK/ERK and HGFR/PI3K/AKT pathways converge to phosphorylate BAD that plays a critical anti-apoptotic role in many types of tumor cells." (PMID 27590512, 2016). "That is, EGFR-expressing cells are targeted by EGFR-CAR NK cells, but oHSV-1 also can kill EGFR-negative tumor cells." (PMID 27050072, 2016). "EGFR, VEGF-A, and the VEGF-A receptor VEGFR-1/2 are believed to play key regulatory roles in tumor tube formation." (PMID 27613831, 2016). "Moreover CTC characterization could provide information about genotypic and phenotypic features of a tumour without the need for an invasive biopsy, for instance the detection of epidermal growth factor receptor (EGFR) mutations in NSCLC patients." (PMID 26913536, 2016). "Among these, concurrent high IHC staining intensity of EGFR and HER2 was detected in 14 (6.4 %) tumours." (PMID 27387915, 2016). "As determined by immunohistochemical analysis, the tumor samples showed various range of reactivity to GFAP, EGFR and the proliferation marker ki67." (PMID 26755664, 2016). "GW627368X therefore effectively inhibits tumor survival, motility, proliferation and angiogenesis by blocking EP4/EGFR interactive signaling." (PMID 27010855, 2016). "Many current research works bet on the combination of an EGFR-TKI with another molecularly targeted agent, for therapeutic tumor resensitization to anti-EGFR-therapy, with interesting preclinical results." (PMID 27528792, 2016). "Cetuximab, a monoclonal antibody targeting the Epidermal Growth Factor Receptor (EGFR), has demonstrated activity in various tumor types." (PMID 25810697, 2015). "Of the 28 patients enrolled in the clinical trial, 13 provided a plasma sample, a tumor tissue sample, and overexpressed and/or expressed HER2 and EGFR, respectively." (PMID 26571496, 2015). "EGFR and SOS1 levels were found to be higher in the p-AKTHIGH, Bcl-2LOW HepG2-transplanted tumor than in the wild type HepG2 tumor." (PMID 25980493, 2015). "The phosphorylated epidermal growth factor receptor (EGFR) signaling pathway was upregulated in the recurrent tumors, and the combined inhibition of EGFR and FGFR1 signaling reduced the collagen-enriched stroma and significantly delayed tumor recurrence." (PMID 26581390, 2015). "At the time of diagnosis the tumor had molecular features consisting of isocitrate dehydrogenase 1 (IDH-1) wild type, epidermal growth factor receptor (EGFR) amplified, and O6-methylguanin-DNA-methyltransferase (MGMT) unmethylated." (PMID 25793136, 2015). "It has been reported that gefitinib, an EGFR inhibitor, reduces cellular proliferation and induces apoptosis in ATC cells, and slows tumor growth in a nude mouse model." (PMID 25940539, 2015). "The SCLC group had strongly positive c-Kit in four tumors, EGFR in two, IGF1R in two, and KDR in three, for a total of 10 (16 %) SCLC tumors with a strongly positive RTK (one tumor was strongly positive for both c-Kit and IGF1R)." (PMID 25989941, 2015).
tumor (continued). "Molecular indication of anti-tumor activity for either monotherapy was supported by reduced MEK/ERK and/or EGFR phosphorylation in PLX4720 and HKI-272 treated groups." (PMID 26023796, 2015). "However, the neutralizing antibody failed to fully abrogate the proliferation below the level of T72 h control, suggesting that despite the predominant role of EGFR in some individual tumours additional constitutive mechanisms exist that might contribute to minimal maintenance of these tumours." (PMID 25721094, 2015). "From the reports of EGFR negative patients benefiting from cetuximab therapy, it may be hypothesised that these patients may indeed have a high ratio of low affinity to high affinity binding receptors and/or EGFR variants within the tumour." (PMID 26149458, 2015). "Activation or overexpression of ErbB such as ErbB2 (HER2) and ErbB3 (HER3) and EGFR has been observed in various types of tumours." (PMID 25977926, 2015). "Inhibition of EGFR and IGF-1R pathways using their respective therapeutic antibodies presented promising results in controlling tumor growth in several preclinical models 24,25." (PMID 25355701, 2015). "The combination treatment of TG101348 and erlotinib obviously decreased the expressions of EGFR, p-EGFR, Bcl-xL and survivin, suppressed the activation of STAT3, induced apoptosis and inhibited tumor growth of EGFR-mutant NSCLC cells in vivo." (PMID 25869210, 2015). "As the tumor and its surrounding microenvironment can affect each other and the (extremely) low prevalence of EGFR and K-Ras mutations in HNSCC would likely preclude a major role for these mutations as predictive biomarker, drug resistance might occur from the tumor microenvironment." (PMID 26032726, 2015). "Epidermal growth factor receptor (EGFR) is a cell surface receptor which plays a significant role in signaling pathways, which regulate cell proliferation, angiogenesis, and tumor metastases." (PMID 25995714, 2015). "Overall, these findings suggest that stroma remodeling during FGFR1 inhibitor treatment is important both for tumor dormancy and recurrence, and, furthermore, that recurrence can be delayed by inhibiting both FGFR1 and EGFR signaling." (PMID 26581390, 2015). "MiR-133a expression was negatively correlated to lymphatic metastasis (r = −0.182, P = 0.042), tumor size (r = −0.253, P = 0.04), clinical TNM stages (r = −0.154, P = 0.087), and EGFR protein expression (r = −0.612, P < 0.001)." (PMID 25903369, 2015). "MET can activate many of the same downstream signaling pathways as EGFR, such as ERK1/2 and PI3K/AKT; additionally, it promotes tumor growth by affecting proliferation, anti-apoptosis, invasion, and angiogenesis in several tumor types." (PMID 26319934, 2015). "Clinically, up-regulation of EGFR can be detected in NPC patient biopsies, as PTPRG can induce dephosphorylation of EGFR and, thus, the downstream PI3K/Akt signaling pathway; this further supports the critical tumor suppressive role of PTPRG in NPC." (PMID 25970784, 2015). "In conclusion, our data indicate that although EGFR expression alone has limited clinical and prognostic significance, EGFR/CXCR4 coexpression identified a subset of PDAC patients with more aggressive tumor characteristics and a significantly worse prognosis." (PMID 25679210, 2015). "For patients whose tumor had high levels of both γ-H2AX and HIF-1α had worse over-all survival, so as with high levels of both γ-H2AXand EGFR." (PMID 25537504, 2015). "In summary, our current findings demonstrate a novel role for RHBDD1 in promoting tumor cell growth through the ADAM-independent cleavage and secretion of proTGFα to activate the EGFR/Raf/MEK/ERK signalling pathway in CRC." (PMID 26300397, 2015). "Results showed that EGFR inhibitors at clinically relevant doses can reduce the regulation of HIF-1α and Notch1 in this tumor type with limited side effects." (PMID 25723392, 2015).
tumor (continued). "Epidermal growth factor receptor (EGFR) is a receptor tyrosine-kinase that is overexpressed in 90 % of HNSCC tumors and is involved in tumor growth, invasion, metastasis, and angiogenesis." (PMID 26319934, 2015). "Some individual tumor nodules from tri-transgenic animals contained human EGFR and were positive for p-ERK, but nodules that appeared to lack human EGFR scored positive for p-ERK, implying that they express only the Kras oncogene." (PMID 26047463, 2015). "EGFR/AKT/ERK signaling is activated and protects tumor cells from cytotoxic doses of ionizing radiation induced DNA damage." (PMID 26546517, 2015). "This region (17q12q21) contains the proto-oncogene HER2, a receptor tyrosine kinase that belongs to the family of the epidermal growth factor receptor (EGFR), whose overexpression is considered a potent tumor driver." (PMID 26075403, 2015). "The high levels of EGFR protein and the downstream pathway including ERK in the cells warrant the subsequent tumor growth, invasion and metastasis." (PMID 26025929, 2015). "Addition of HGF or EGF phosphorylated MET or EGFR, respectively, and demonstrated phosphorylation of Akt and ERK1/2 as well as increased tumor cell viability." (PMID 26496080, 2015). "Immunostaining for markers of tumor proliferation (Ki-67), apoptosis (caspase-3), tumor-initiating cells (ALDH), macrophage infiltration (F4/80), E-cadherin, and EGFR signaling (phospho-EGFR, p-EGFR) were compared between control and 10% MSC primary tumors." (PMID 25887413, 2015). "In this signaling model of tumor progression, the abnormally high expression of KLF8 in the cancer cells ensures the high level of EGFR." (PMID 26025929, 2015). "We analyzed the clinical data of 139 BIDC cases retrospectively, detecting EGFR, CD44, and CD24 expressions in tumor tissue using immunohistochemistry." (PMID 25429827, 2015). "HER-2, also referred to as c-erbB-2, is a type of oncogene with an homologous sequence with the virus oncogene as well as the oncogene of epidermal growth factor receptor (EGFR), and is overexpressed in various types of tumor." (PMID 25780431, 2015). "It is often claimed that positivity for EGFR and HER2 receptors indicate aggressive tumor cells and bad survival prognosis and, if so, the most aggressive cells are attacked with the radiation." (PMID 25810701, 2015). "ADAM17 and EGFR increase the expression of HIF-α, and HIF-α then activates VEGF and VEGFR to stimulate tumor angiogenesis." (PMID 25544346, 2015). "The tumor suppressor let-7a miRNA was transfected into HEK293 cells expressing EGFR peptide, and exosomes produced from these cells significantly decreased HCC70 tumor growth in mice." (PMID 26601108, 2015). "Despite significant differences in tumor cellularity, the quality (amplification of internal positive control in real-time PCR) and the quantity of DNA obtained from different types of materials was similar, and so was the DNA concentration in samples with and without EGFR mutations." (PMID 25086987, 2015). "Because ∼40% of PCas express epidermal growth factor receptor (EGFR), expression of which is correlated with tumour recurrence and high Gleason score, the receptor is assumed to be a potential molecular target for advanced PCa." (PMID 26113609, 2015). "By using KCI-10-40X1, a PDX model derived from a GBM patient with EGFRamp, we found that a combination of V-4084 and erlotinib inhibited KCI-10-X1/erl-res tumor growth and provide additional evidence to treat GBM EGFRamp patients targeting both EGFR and MET." (PMID 26381735, 2015). "We also demonstrate that one of the degradation mechanisms of AXL is associated with PS-RIP, and thus, enhancing the degradation of AXL can effectively inhibit cell proliferation and tumor growth in NSCLC and EGFR-TKI-resistant NSCLC cells." (PMID 25760142, 2015).